CXCR3 (C-X-C motif chemokine receptor 3)
Diseases named in the same sentence as CXCR3 in open-access papers (continued):
Sharing a sentence is not in itself a finding about the gene and the disease.
osteosarcoma (continued). "The clinical data from a total of 98 cases with osteosarcoma and the corresponding expression data of CXCR2, CXCR3, CXCR4, and CXCR5 were included." (PMID 31696204, 2019). "The Kaplan–Meier analyses were conducted to estimate the survival impact of expression of CXCR2, CXCR3, CXCR4, and CXCR5 in osteosarcoma." (PMID 31696204, 2019). "Treating mice with CXCR3 antagonist AMG487 significantly decreases lung metastases and reduces tumor expansion within the lungs in two murine models of osteosarcoma." (PMID 24259307, 2013). "In the present study, we observed that the expression of CXCR2, CXCR4, and CXCR5 were not correlated with the prognosis, but CXCR3 low expression was correlated with poor prognosis in osteosarcoma." (PMID 31696204, 2019). "Also, in a study on pulmonary metastasis from osteosarcoma, it was concluded that targeting CXCR3 could specifically inhibit tumor metastasis without adversely affecting the anti-tumor host response." (PMID 36479091, 2022). "However, the relationship between CXCR3 and the prognosis in osteosarcoma has not been studied." (PMID 31696204, 2019).
prostate carcinoma (14 papers, 2012 to 2026). A carcinoma that arises from epithelial cells of the prostate gland. "Here, we examined the expression and function of two CXCR3 variants in human prostate cancer biopsies and cell lines." (PMID 22236567, 2012). "CXCR3 has been shown to be downregulated in prostate cancer bone metastases in comparison with lymph node metastases." (PMID 39146303, 2024). "We also showed that CXCR3/CXCL10 axis plays a significant role in prostate cancer lung metastases in comparison to bone metastases." (PMID 39146303, 2024). "They found that CXCR3 mRNA and protein levels were higher in prostate cancer tissue specimens than in normal tissues, and the levels of CXCR3A mRNA were higher than those of CXCR3B mRNA." (PMID 36479091, 2022). "We previously investigated the roles of CXCR3 isoforms in prostate cancer (PCa) and found that the predominant CXCR3 isoform shifts from CXCR3-B to CXCR3-A during malignancy." (PMID 31831069, 2019). "In primary prostate cancer samples, somewhat upregulated CXCR3 staining was observed which was quantified by the percentage of positive-stained cells." (PMID 22236567, 2012). "More importantly, CXCR3 splice variants exhibited different mRNA expression profile-CXCR3A mRNA level was high and CXCR3B mRNA was low in prostate cancer compared to normal prostate." (PMID 22236567, 2012). "Targeting CXCR3 may enhance T cell infiltration into tumors, especially in cancers such as bladder and prostate cancer, where TRM cells are critical for anti-tumor immunity." (PMID 40066439, 2025). "However, further experimental studies are needed to clarify the specific mechanistic role of CXCR3 in prostate cancer." (PMID 40786052, 2025). "For instance, Shen and his colleagues proved that aberrant expression of CXCR3 might suppress the proliferation and invasion of prostate cancer." (PMID 31240220, 2019). "CXCR3 was upregulated and played a predominant role in the tumorigenicity of prostate cancer." (PMID 31781593, 2019). "Examining single cells, CXCR3 was predominantly on the cell membrane in normal prostate tissue and primary carcinomas but this localization was replaced with a whole cell stain in metastatic prostate cancer tissue (enlarged boxes)." (PMID 22236567, 2012). "Since CXCL4/PF4 and CXCL10/IP10 represent the main CXCR3 ligands found during platelet degranulation and thus any hemorrhage and deep in reactive/wounded stromal compartment respectively, we examined functions of these two CXCR3 chemokines on prostate carcinoma cell functioning." (PMID 22236567, 2012). "Herein, we dissect CXCR3 functioning in prostate carcinomas and derived cell lines." (PMID 22236567, 2012). "In prostate cancer, Andrographolide has been known to inhibit cell viability and cell migration by modulating CXCL11, CXCR3, CXCR7, and IL-16 expression." (PMID 30800220, 2019). "Isoform switching in various genes (such as PKM, CXCR3 and FGR2) during cancer development has been described in several cancer types including prostate cancer, and likewise tumour-specific isoforms of known genes have been identified previously." (PMID 27683107, 2016). "Unsurprisingly, the CXCR3 chemokines blocked RWPE-1 cell invasion through a Matrigel matrix barrier, but increased the invasiveness of both prostate cancer lines." (PMID 22236567, 2012). "Interestingly, CXCR3A mRNA was increased while CXCR3B mRNA was decreased in the prostate cancer samples compared to normal prostate controls, suggesting that the switch of CXCR3 isoform expression may play an important role in prostate cancer dissemination, invasion and metastasis." (PMID 22236567, 2012). "CXCL10 and CXCL11 as well as CXCR3 are upregulated in lymph node-positive primary prostate cancer in comparison to lymph node-negative prostate cancer." (PMID 39146303, 2024). "Even though CXCR3 has been reported as a cell growth regulator in select cancers, CXCR3-chemokines did not alter the cell proliferation in the prostate cancer lines tested (data not shown)." (PMID 22236567, 2012).
prostate carcinoma (continued). "This suggests that CXCR3/CXCR3B internalization and turnover might be occurring in advanced prostate carcinoma cells, indicative of auto- and para-crine stimulation." (PMID 22236567, 2012).
Granuloma (13 papers, 2005 to 2025). A compact, organized collection of mature mononuclear phagocytes, which may be but is not necessarily accompanied by accessory features such as necrosis. "Effector T cells expressing CXCR3 are found within granulomas and are associated with granuloma formation through neutrophil recruitment via CXCR3 signaling." (PMID 36406405, 2022). "CXCR3+ CD4 T cells are efficient in localizing lung parenchyma around the lymphocytic cuff of TB granulomas and rarely in the myeloid core." (PMID 34745081, 2021). "The density of several transcripts including Ccr6, Cd19, and Il12, and to a lesser degree Cd3e, Cxcr3, and Cd8b mRNA was increased in the lymphoid in relation to the epithelioid areas after a supervised annotation of the lymphoid and the epithelioid areas of the granulomas based on H&E staining." (PMID 31015452, 2019). "Levels of Cd68, Inos, Cxcr3, Tcrb, and Ifng transcripts were higher in NOG than in the center (GC) or the rim (GO) of the large and the smaller encapsulated granulomas (SG)." (PMID 31015452, 2019). "Recent data show that T cells expressing CCR6, CXCR3, and CXCR6 act coordinately with respective ligands and Th1 inflammatory cytokines in the alveolitic/granuloma phases of the disease." (PMID 18811966, 2008). "Chemokine receptors, CXCR3 and CXCR6 are co-expressed by Th1 cells infiltrating the lung and the granuloma of patients with sarcoidosis." (PMID 18811966, 2008). "Previous studies indicated that IFNγ mediates expression and secretion of chemokines CXCL9, CXCL10, and CXCL11 in macrophages, resulting in the recruitment of CXCR3 bearing CD4+ Th cells and CD8+ Tc cells into the lung and granuloma formation in humans and mice." (PMID 39464896, 2024). "In mice models of granulomatous disease induced by Propionobacterium acnes, CXCL10 has been shown to be necessary for the formation of Th1 lymphocyte clusters in draining lymph nodes, and blockade of CXCR3 (the receptor for CXCL9 and CXCL10) and CCR5, inhibits the formation of granulomas in lungs." (PMID 24199653, 2013). "Furthermore, recent data in the animal model suggest that CXCR3/CXCL9, CXCL10, CXCL11 interactions are central in the pathogenesis of hypersensitivity reactions to Saccharopolyspora rectivirgula (SR) and successive granuloma formation." (PMID 15725351, 2005). "Furthermore, at week 24, there was no cholestasis or granulomas in CXCR3−/− PBC mice." (PMID 21647407, 2011).
Hepatitis (13 papers, 2012 to 2023). Inflammation of the liver. "By engraftment of NSG mice with PBMCs from patients followed by several injections of hHSCs and CCl4, injected human inflammatory cells were CXCR3-dependently recruited into the liver and caused liver inflammation." (PMID 35418987, 2022). "Indeed, CXCR3 can activate and recruit T cells, such as Th17 cells, to the liver, causing liver inflammation and playing a crucial role in the development of viral-related liver inflammation and non-alcoholic steatohepatitis." (PMID 35418987, 2022). "We investigated the role of CXCR3 in Th17 recruitment in vivo in two mouse models of liver inflammation." (PMID 22796894, 2012). "The observation of decreased CXCR3 expression combined with the fall of lymphocyte number in the liver during hepatitis may explain that despite their induction in IL-33 KO context, these chemokines would not be able to interact with their target cells." (PMID 28607531, 2017). "Similarly, in human chronic liver disease and mouse models of hepatitis, CXCR3+ Treg cells accumulate in the liver, where they dampen immune-mediated tissue damage." (PMID 25946021, 2015). "The sequential requirement for CXCR3 and CCR1 for the mobilization of splenic NK cells and their subsequent accumulation in the liver was demonstrated in a murine Con A-induced hepatitis model." (PMID 31704965, 2019). "We quantified the fraction of hepatic CD4+ T cells expressing CXCR3, the receptor for CXCL9 and CXCL10 that were strongly up-regulated at an early stage of Con A-induced hepatitis." (PMID 26052942, 2015). "For example, the predominant TRM cells associated with the pathogenesis of AIH are CD8+CD69+CD103+ TRM cells that highly express PD1, CXCR3 and granzyme B; whereas liver TRM cells of patients with acute hepatitis A are mainly CD8+CD69+CD103- TRM cells that express high levels of HIF-2α." (PMID 36172356, 2022). "This analysis revealed that a conventional CXCR3+ Th1 gate excluded many cells expressing intermediate levels of CXCR3 in the hepatitis patient but not the control." (PMID 29289977, 2018). "Therefore, stimulation of TLR3 and 9 promotes homing of CXCR3+ and CXCR6+ T cells, including autoreactive T cells, resulting in bystander hepatitis." (PMID 23110209, 2012).
multiple myeloma (13 papers, 2014 to 2025). "To further assess the value of surface CXCR3 expression as a marker for myeloma-associated CD8 + T cells, we subjected BM CXCR3 + and CXCR3- CD8 + T cells from an independent cohort of 7 MM patients to bulk RNA-sequencing." (PMID 39613747, 2024). "Upregulation of CXCR3 ligands in multiple myeloma patients with active disease corresponded to marked down-modulation of CXCR3 expression levels by BM NK cells, an event that was linked to reduction of NK cell localization in the BM in multiple myeloma-bearing mice." (PMID 27766097, 2016). "n multiple myeloma, CXCR3 expression increases across different pathological stages, with higher expression observed in stage III compared to stage I." (PMID 40786052, 2025). "ChIP-on-chip data revealed that heparanase bound to regulatory regions of myeloma-related genes (i.e., CXCL12), encodes for SDF-1, CXCR4, CXCL2, CXCR3, CCL27, CX3CL1, and LCN2." (PMID 36980254, 2023). "IP-10 and its receptor CXCR3 have been shown to regulate the proliferation and survival of myeloma cells." (PMID 32587468, 2020). "Our data demonstrate for the first time that it is possible to increase activated BM NK cell infiltration with beneficial anti-myeloma effects by genetic deletion of Cxcr3 gene or by in vivo administration of anti-CXCR3 specific mAb." (PMID 31699153, 2019). "In this study we demonstrated that promotion of NK cell accumulation in BM by CXCR3 targeting is critical for the long-lasting anti-myeloma response of IL-15 activated NK cells." (PMID 31699153, 2019). "CXCR3 inhibition increases BM infiltration of IL-15 activated cells, thus improving and prolonging their anti-myeloma effect up to 7 days." (PMID 31699153, 2019). "Thus, they are poorly effective in the short time frame, even upon deletion of Cxcr3 gene, but their anti-myeloma effect becomes important later after re-stimulation with IL-15." (PMID 31699153, 2019). "In addition they also observed increased levels of CXCL10 within the bone marrow of patients with multiple myeloma and this was correlated with a decrease in the number of CXCR3+ NK cells within blood." (PMID 28389623, 2017). "Moreover, activated tumour-specific T cells that express CXCR3 were shown to infiltrate CXCL10-expressing myeloma cells more efficiently than non-CXCL10-expressing myeloma cells." (PMID 26115406, 2015). "On the other hand, IL-12/15/18 activated cells display a longer capacity to restrain multiple myeloma growth in vivo compared to IL-15 activated cells, that seems independent of CXCR3 function due to reduced expression levels of this receptor." (PMID 31699153, 2019). "It was noteworthy, however, that the frequency of CCR4+ T cells was substantially greater than the CXCR3+ population, suggesting that CCR4-binding chemokines may have a predominant influence on recruitment and retention of T cells to marrow in patients with myeloma." (PMID 28389623, 2017).
Obesity (12 papers, 2018 to 2025). Accumulation of substantial excess body fat. "After HFD feeding, we observed an increase in AT-resident CD8+CXCR3+ T cells in siglec-E KO mice, compared to WT mice, implicating that the deletion of siglec-E in AT inflammation leads to an exaggerated obesity-associated low-grade chronic inflammation." (PMID 39967660, 2025). "Recent evidence also suggests that CXCR3-deficient mice are protected from macrophage infiltration and hepatocellular damage in obesity." (PMID 31921154, 2019). "Previously, we and others reported that the increased adipose expression of CXCL10 in individuals with obesity was associated with inflammatory (IL-1β expression, C-reactive protein levels) and other factors (BMI, CXCR3, and reduced neovascularization causing adipose tissue hypoxia)." (PMID 39065674, 2024). "The chemokine receptor CXCR3 and its ligands facilitate immune cell trafficking in tissue and CXCR3-expressing adipocytes modulate inflammation during obesity." (PMID 39967660, 2025). "We observed a significant increase in CXCR3+ T cells in mouse AT during high fat diet-induced obesity (DIO)." (PMID 34248964, 2021). "Recent findings suggest that circulating CD4+ T-cells adopt an effector memory (CXCR-3+CD62L−) phenotype with human obesity in response to a metabolically driven adaptation within T-cells via the p110δ subunit of phosphoinositide 3-kinase (PI3K)." (PMID 29479350, 2018). "Further, CXCR3 expressing CD8+ T cells also play a crucial role in diet-induced obesity." (PMID 39967660, 2025). "At the same time, the expression of chemokines (Cxcl9, Cxcl10) and the chemokine receptor CXCR3, which are key for traffic to the tumor and extravasation, were highly down-regulated in obesity, suggesting that lower chemokine levels prevented effective recruitment of immune cells to the tumor site." (PMID 35103755, 2022). "Adipocytes also express CXCR3 and modulate obesity-induced inflammation." (PMID 34248964, 2021). "In the present study, we used a mouse model of HFD-induced obesity to study the relationship(s) between adipocytes, both CD4+, CD8+ T cells, CXCR3 expression, and macrophage function in the obese AT microenvironment." (PMID 34248964, 2021). "Interestingly, our results further confirmed these findings, as the percentage of the mo-MDSCs cells expressing CXCR3 and CD62L was rapidly diminished after surgery, supporting the correlation between peripheral immune cell dysfunction and obesity." (PMID 37266430, 2023). "Furthermore, the expression of chemokine signaling molecules, including CCL24, CCR6, and CXCR3, was altered in accordance with female-specific fluctuations in VAT-Treg in obesity." (PMID 32240221, 2020). "Using the terms, hypothalamus, hypothalamic, obesity, inflammation, Cxcr3, and Cxcr6, we could find no prior publications." (PMID 39535032, 2024). "However, no previous study has evaluated CXCR3 in the hypothalamus in the context of obesity." (PMID 39535032, 2024). "In addition, obesity has been reported to alter the trafficking profiles of T-cells, where memory CD4+ T-cells from HFD-fed mice preferentially migrate to non-lymphoid (i.e. peripheral tissues) in a CXCR3-dependent manner, even in chow-fed mice." (PMID 36891817, 2023).
HIV-1 infection (11 papers, 2012 to 2025). The type species of lentivirus and the etiologic agent of acquired immunodeficiency syndrome (AIDS). "HIV-1 infection was associated with a significant decrease in the frequency of CXCR3+CD7+CD56+CD16+ NK cells." (PMID 24351015, 2013). "By comparison, approximately 70% of CD7+CD56brightCD16neg immature NK cells express CXCR3, and HIV-1 infection is associated with a significantly lower frequency of CXCR3+ CD7+CD56brightCD16neg immature NK cells compared to healthy controls." (PMID 24351015, 2013). "These cells were also the most permissive to HIV-1 infection and are the main source of IL-21 after in vitro stimulation in contrast to CXCR3− TFH cells." (PMID 26034905, 2015). "The majority of TFH-cells expressed CCR5 and CXCR3 and are the most permissive to HIV-1 infection." (PMID 26034905, 2015). "Of note, a decreased frequency of CXCR3+CD8+ T-cells was reported in advanced HIV-1 infection that might contribute to cytotoxic T-lymphocyte dysfunction." (PMID 22470433, 2012). "Similar reports are found in HIV-1 infection, whereby continuous stimulation of immune system impairs the migration ability of circulatory CCR6+ CXCR3+ Th cells from blood to peripheral organs." (PMID 31635276, 2019). "It has been shown that CCR6+CCR4+, CCR6+CXCR3+ and CCR6+CD90+ Th17 cell subsets are highly permissive to HIV-1 infection." (PMID 28509877, 2017). "Our study shows that CXCR5+PD-1++ CCR5+ TFH cells were the most permissive CD4+ T cell subset to HIV-1 infection and correlated with the expression of cell surface markers PD-1, CCR5, and CXCR3." (PMID 26034905, 2015). "IP-10 binding CXCR3 and CD4+CXCR3+ T cells are the main targets of HIV-1 infection." (PMID 30541557, 2018). "Furthermore, we find a strong correlation between the expression of CXCR3, PD-1, CCR5, and the permissiveness to HIV-1 infection." (PMID 26034905, 2015).